CD4 (CD4 molecule)
Diseases named in the same sentence as CD4 in open-access papers (continued):
Sharing a sentence is not in itself a finding about the gene and the disease.
tumor (continued). "To address the potential migration trajectories of T cells, we analyzed the clonotypes shared among five related samples including tumor tissues, nearest non-cancer tissues, LN, distal normal tissues and P1, and identified more shared CD8+ T clones between different tissues than CD4+ T clones." (PMID 35831283, 2022). "Many different types of lymphocytes have been identified in the TME (CD4+ with/without suppressor FoxP3+ expression, CD8+ with/without PD-L1 expression, and M2 macrophages), reflecting the complex interplay between tumor antigenicity and host immune reaction." (PMID 35158822, 2022). "apCAFs express MHC II molecules but lack the classical costimulatory molecules (e.g., CD40, CD80, and CD86) required to induce activation and clonal expansion of CD4+ T cells after T cell receptor (TCR) ligation; therefore, their role in tumor immunity has not been verified." (PMID 36010986, 2022). "By analyzing the immune landscape of TH-MYCN tumors in mice, we found that JQ1 had no major impact on infiltrating immune cells into the tumor microenvironment but significantly increased the percentage of CD8+ PD-1+, conventional CD4+ PD-1+, and Treg PD-1+ cells." (PMID 36139358, 2022). "However, the CD4 and CD8 T cells in the first tumor-cured TRG-treated mice and other controls did not produce IFN-γ in response to CT-26 lysate exposure." (PMID 35643505, 2022). "Consequently, these data suggest that IFNγ delivery at the tumor microenvironment alone, or in absence of CD4-TAM direct interaction, would not suffice for TAM reeducation and, most importantly, tumor clearance." (PMID 35903540, 2022). "Specifically detects human CD4+ T cells without impacting their abundance, proliferation, and activationCan visualize various peripheral tissues in addition to orthotopically implanted GBM tumours." (PMID 36297474, 2022). "By day 22, untreated mice show advanced tumor growth, while SV.IgGOX40.IL-12 treated mice show little or no MOSEC.Fluc.p11 tumors.Depletion of CD4 and CD8 T cells, however, diminishes SV.IgGOX40.IL-12 treatment indicating the importance of T cell immune response to the therapeutic process." (PMID 36611875, 2022). "Therefore, increased Foxp3/CD8, PD-1/CD4, and PD-1/CD8 ratios and VASH-1 expression in the tumor tissues were considered to suppress anti-tumor immunity more markedly in NEC than in non-NEC components of MiNENs." (PMID 35565281, 2022). "Only the CD11ahiCD49dhi CD4 T cells, but not the CD11aloCD49dlo subset, produced IFN-γ when stimulated with mCAR12/mCDK12 peptides in vitro, suggesting that CD11ahiCD49dhi T cells represent an antigen-experienced subpopulation in the KPC4580P tumor." (PMID 36569934, 2022). "The CCL22 receptor CCR4 is highly expressed on Tregs in GBM tissues, and other CD4 and CD8 cells in tumor tissues do not express this receptor, suggesting that the recruitment of Tregs in GBM may depend on the action of chemokines." (PMID 36466873, 2022). "TMZ significantly decreased the Treg/CD4+ T cell proportion when given at very low doses but not at high standard doses.Treg depletion alone, detected in LDM TMZ-treated rats, was not sufficient to significantly inhibit tumor progression, compared to control." (PMID 36362482, 2022). "However, CTLA-4 expression, on tumor-specific CD8+ T cells and CD4+ Foxp3+ Tregs was not affected by anti-CD73 treatment in this tumor." (PMID 35711418, 2022). "After 8 and 24 h coculture, expression of all three exhaustion markers was significantly upregulated in both CD8+ and CD4+ HER2-, but not ctrl-, CAR T cells, consistent with the current view that tumor cell/T cell interactions in the TME induce expression of exhaustion markers in T cells." (PMID 36591284, 2022). "We did not observe any differences that could explain the anti-tumor effect of COS, but we did see a trend towards higher percentages of CD4+ and CD8+ cells after treatment with ICIs." (PMID 35631632, 2022).
tumor (continued). "When we confirmed the scRNAseq results using flow cytometry, we observed that the overall recruitment of immune cells, including CD4 T cells and CD8 T cells, was not significantly affected by aPD-1; however, the number of tumor-specific CD8 T cells was increased by aPD-1." (PMID 36591276, 2022). "Total and CD8+ MAIT cells as well as NM‐CD4+, NM‐CD8+, and DN T cells, but not CD4+ and DN MAIT cells, showed increased fractions of PD‐1‐expressing cells and levels of PD‐1 expression within the tumor microenvironment compared to circulating cells." (PMID 35028137, 2022). "It is not yet clear what determines if CD8+ T cells or CD4+ T cells or both will mediate antitumor immunity: whether this depends on Fas/Fas ligand interactions, MHC class I/II expression, the tumor type, the type of treatment, or other mechanisms." (PMID 36159781, 2022). "Additionally, we observed that, unlike conventional CD4 + CAR-T cells (28z-CAR), the metabolic activity of conventional CD8 + CAR-T cells surprisingly decreased with tumor stimulation." (PMID 35869100, 2022). "Though no changes were seen in the level of T helper cells in the tumor, the elevation in IFN-γ production by the CD4+ cells suggests a tilt in the balance between the anti-tumorigenic type 1 and the immunosuppressive type 2 helper cells in the TME, in favor of the former." (PMID 36430552, 2022). "There was no significant change in CD4 T cell abundance observed across conditions, yet an increase in the number of CD8+ T cells within the tumor T cell population of drug resistant primary tumors, compared to the drug-sensitive tumors (58.1%, 47.8% respectively) was observed." (PMID 35924165, 2022). "However, the CD4+ and CD8+ T cells appear to be more prevalent in the tumor area from patients who did not relapse." (PMID 35394115, 2022). "Moreover, strong positive correlations were observed between levels of FoxP3+Helios+ Tregs with CD4+TIM-3+ T cells and CD4+LAG-3+ T cells (r = 0.767, p < 0.0001; r = 0.749, p < 0.0001, respectively) in tumor tissues but not in circulation or normal tissues." (PMID 35455287, 2022). "Furthermore, strong positive correlations were found between levels of FoxP3+Helios− Tregs with CD4+TIM-3+ T cells and CD4+LAG-3+ T cells (r = 0.636, p = 0.002; r = 0.502, p = 0.017, respectively) in tumor tissues but not in PBMCs and NILs." (PMID 35455287, 2022). "CD4+ have been previously observed to be the primary mediators of tumor clearance in a manner that is independent of CD8+ T cells but reliant on IFNγ, and the partnership between CD4+ T cells and macrophages has been documented as one of the mechanisms driving this effect." (PMID 36123677, 2022). "The tumor usually contains a heavy infiltrate of EBV-negative non-malignant leukocytes that are primarily composed of CD8+ and CD4+ T cells and subsets of natural killer (NK) cells, B cells, mast cells and various types of myeloid cells including monocytes, macrophages, and neutrophils." (PMID 33718235, 2021). "Last but not least, to evaluate the functional reinvigoration of tumor-infiltrating lymphocytes, a sign for successful immune checkpoint blockage, we examined the functional effect of PPA1-DOX on restoring intratumoral CD4+ and CD8+ T cells by immunohistochemistry staining." (PMID 34858817, 2021). "However, among the tumor-infiltrating lymphocytes, CD3, CD4, and CD8 had prognostic implications, but not FOXP3 and immune cell score." (PMID 34898543, 2021). "Tumor growth control was still observed in the hexatherapy minus OX40+4-1BB and hexatherapy minus Ad-CEA+N-803 groups, even though peripheral CD4+ T cell activity was not profound in these cohorts." (PMID 33602696, 2021). "This therapy activates the specific and non-specific immune response against vessels and tumor cells, inhibits angiogenesis, reduces the M2 phenotype of TAMs, induces the recruitment of CD8+ and CD4+ lymphocytes, and inhibits primary tumor growth and metastases." (PMID 33800564, 2021).
tumor (continued). "In this study we could not find any correlation between PD1 or PD-L1 expression or CD4+ and CD8+ tumor infiltration and prognosis." (PMID 34573939, 2021). "Furthermore, CD4+ cells became pro-tumorigenic in TC-1/dCD80-1-induced tumors, while CD8+ cells controlled tumor growth regardless of CD80 expression." (PMID 33923750, 2021). "In addition, on mice treated with only anti-PD-L1, CD4+ accumulated in tumor margin without invading tumor tissue; only on mice treated with combination of anti-VEGF and anti-PD-L1 it was possible to see CD4+ T cells and CD8+ T cells infiltrate tumor tissue." (PMID 36046087, 2021). "Furthermore, in both CD4+ and CD8+ T cells, interaction with tumor cells did not influence the production of IFN-gamma." (PMID 34440813, 2021). "Blocking TGF-β signaling in CD4+ T cells but not CD8+ T cells restrained tumor growth by remodeling the TME and inducing tumor vasculature reorganization, leading to cancer cell death; this process was dependent on the TH2 cytokine interleukin-4 (IL-4), but not the TH1 cytokine interferon-γ (IFN-γ)." (PMID 34917620, 2021). "However, unlike in extracerebral metastases, neither stromal PD-L1 nor tumor PD-L1 expression correlated with CD3+, CD4+, or CD8+ TIL content within intracerebral metastases." (PMID 32974852, 2021). "Interestingly, we also observed that the proportion of CD4 and CD8 T-cells in non-tumour Inv mice is 5 times higher than that in non-tumour Null mice." (PMID 34511060, 2021). "In addition, the high expression of DHX37 is found in both activated CD8+ and CD4 T+ cells, and the expression of DHX37 is significantly higher in exhausted tumor infiltration lymphocyte (TILs) compared to nonexhausted ones." (PMID 33490273, 2021). "Moreover, the numbers of tumor-infiltrating CD3 + T cells and CD8 + T cells but not CD4 + T cells and CD11B + myloid cells, were also significantly elevated in mice administered with a combination of capmatinib and anti-PD-L1 antibody." (PMID 34479614, 2021). "In animal models, a successful anti-cancer immune response does not simply rely on MHC-I–restricted neoantigens to drive tumor antigen-specific CD8 T cell responses; the presentation of neoantigens on MHC class II (MHC-II) molecules to CD4 T cells within tumors also plays an essential role." (PMID 34290401, 2021). "Similarly, the KLRC1 expression level had negative correlation with tumor purity and positive correlation with infiltrating levels of B cell, CD8+ T cell, CD4+ T cell, Macrophage, Neutrophil and Dendritic cell." (PMID 34368124, 2021). "Similar to the tumor compartment, in the spleen, a marked expansion of CD8+ T and NK cells was observed in THOR-707-treated animals, while no significant change in CD4 Treg population was observed, resulting in a progressive increase in the splenic CD8+ T/Treg ratio at days 5 and 7 post-dose." (PMID 34373459, 2021). "CD4+ T cells, in contrast, did not produce detectible IFN-γ in the draining lymph nodes at either time point, but displayed a small but significant increase in the number of cells producing IFN-γ within the tumour mass at both time points." (PMID 33925140, 2021). "Moreover, the IL-21-producing T cells in the tumor tissues were FOXP3 negative, and the majority of these cells (84.5 ± 3.3%) were CD3 and CD4 positive." (PMID 34026621, 2021). "Besides, Fam20C expression has no obvious relation with tumor purity and infiltrating levels of B cells, CD8+ T cells, CD4+ T cells, macrophages, and neutrophils in DLBC, at the same time in GEPIA showed Fam20C played a protective role of prognosis in DLBC." (PMID 33306121, 2021). "Further clustering analysis for T cell and myeloid compartments based on defined markers led to the identification of four CD4+ and two CD8+ T cell subsets, eight monocyte/macrophage subsets, and six dendritic cell (DC) subsets in most of the patients from both tumor and nonmalignant tissues." (PMID 34921160, 2021).
tumor (continued). "In colorectal cancer, the lack of METTL3 or METTL14 increases cytotoxic tumor-infiltrating CD8+ T cells; enhances the production of interferon- (IFN-) γ, CXCL9, and CXCL10; and promotes the recruitment of CD8+ and CD4+ effector T cells that inhibit tumor growth." (PMID 34858499, 2021). "In addition, CD4+ T cells have the ability to control tumor growth in different ways, even in the absence of MHC-class II on the tumor cells." (PMID 33546283, 2021). "Approximately four weeks after cell line challenge, tumours continued to grow in the majority of mice depleted of CD8β+ T cells or TCRβ+ T cells, but not in mice depleted of CD4+ T cells, suggesting that CD8+ T cells also play a vital role in the prevention of SCC tumour progression." (PMID 33925140, 2021). "Subsequently, we sorted separate sets of CD4+ TEG011 cells that co-expressed either exogenous CD8αα (CD4+CD8α+) or CD8αβ (CD4+CD8αβ+) as well as TEG011 cells expressing only endogenous CD4 and CD8 as negative and positive controls for tumor recognition, respectively." (PMID 34759930, 2021). "CD4+ or CD8+ T cell infiltration did not change after irradiation alone, which indicated that commonly used dose of X-ray irradiation was insufficient to alter the immunological tumor microenvironment." (PMID 33420008, 2021). "TGF-β produced by CAFs excludes CD4 + and CD8 + T cells from entering the tumor and an anti-TGF-β antibody could reverse tumor T cell exclusion and sensitize tumors to PD-L1 treatment." (PMID 34579759, 2021). "In our study, IFN-γ expression in CD8+ T cells in both LNs and tumors was significantly increased, whereas IFN-γ expression was not altered in other immune cells, such as CD4+ T cells, macrophages, and DCs after topical IMQ stimulation in the murine tumor model." (PMID 34439104, 2021). "In addition, the proportion of CD4+LAG-3+ and CD8+LAG-3+ T cells in MPE after chemotherapy are similar to tumor tissue in one study, but not another." (PMID 33987104, 2021). "However, compared with the control group, HT treatment did not increase CD4+ T and CD8+ T infiltration in tumor tissues." (PMID 34858184, 2021). "However, the results of ‘Gene’ module indicated that the gene expression of CCNB1 was positively correlated with tumor purity, B cell, CD8 + T cell, macrophage, neutrophil, but not with the immune infiltration level of CD4 + T cell." (PMID 34077304, 2021). "Typically, tumor cells are CD2+, CD3+, CD4+, CD8−, CD5+, and CD25+, and CD7 is often negative." (PMID 34830926, 2021). "In addition, BALB/c CD4+ T cells activated using BALB/c DCs, which were not reactive to the B6 host, also failed to control tumor progression." (PMID 34625113, 2021). "However, the frequencies of IFN-γ-producing CD4+ T cells and CD8+ T cells in the tumor-draining lymph nodes of mice were not altered by low-dose TSA treatment." (PMID 33564072, 2021). "CD4+ TEG011_CD8α cells produced a significantly higher IFNγ level compared to CD4+ TEG011, which was equivalent to those of TEG011 bulk cells against all tumor targets, without affecting healthy cells." (PMID 34759930, 2021). "In contrast, M2 macrophages are an unfavorable factor in terms of promoting tumor growth, and we observed negative correlations between M2 macrophages and CD8+ T cells (−0.37); M0 macrophages and CD4 memory activated T cells (−0.37); and M0 macrophages and CD8+ T cells (−0.37)." (PMID 33854974, 2021). "The tumor cells of MF are usually positive for CD3 and CD4 and negative for CD8." (PMID 34574062, 2021). "Furthermore, we found that the frequencies of total, CD4+, and CD8+ T cells in the spleen were not altered in response to HFD treatment in tumor-seeded mice." (PMID 33060562, 2020). "Indeed, we corroborated that tumor-infiltrating CD8+ and CD4+ T cells were not affected by depletion of circulating T cells in the OVA + Porins-immunized mice 21 days post MO4 inoculation." (PMID 33240271, 2020).
tumor (continued). "An increase in CD45+CD3+CD4+ expressing T-cells, and a non-significant increase in CD45+CD3-NK1.1+ expressing NK cells, was seen in 3 × 5 Gy RT-treated tumours compared to untreated control tumours." (PMID 32641865, 2020). "Tumor infiltrating lymphocytes, considered as selected population of T-cell with a higher specific immunological reactivity against tumor cells than the non-infiltrating lymphocytes, are mainly composed of CD3+CD4+T cells and CD3+CD8+T cells." (PMID 33613544, 2020). "In addition, we did not further study the subgroups of CD4 + and CD8 + cells in the tumor immune microenvironment and failed to further explore the detailed mechanisms of immunosuppression in liver metastases." (PMID 33308232, 2020). "Overexpression of IL-1β in mammary 4T1 tumor cells can modify MDSC phenotype (more CD8, CD80, CD83, and CD14 expression and lower CD44 and B220) in vivo, while it does not change their capacity to dampen CD4 and CD8 T-cells’ activation/proliferation." (PMID 32635472, 2020). "However, regulatory T cells, tolerogenic dendritic cells, and non-functional T cells (CD4+ and CD8+) can induce immunosuppression in the tumor microenvironment." (PMID 33197890, 2020). "We found that the cured mice depleted of CD8+ T cells, but not CD4+ T cells, did not reject either local or distant rechallenges, indicating that CD8+ T cells are the key players for induction of memory responses against local and distant tumor rechallenges." (PMID 32286326, 2020). "TEVs abrogated the effect of CD4+, but not CD8+, CAR T cells independent of whether the tumor cells from which they were derived expressed NTRK receptors." (PMID 32296437, 2020). "Additionally, they focused on enrichment for tumour reactive CD8+ T cells, elimination of non-specific CD4+ T cells, and depletion of regulatory T cells (Tregs) that are known of their potent immunosuppressive activity." (PMID 32183246, 2020). "The tumor cells in ETTL-1 express CD3 and CD7, but not CD4, CD8, CD5, or CD56." (PMID 33457319, 2020). "In our study, we could not find a strong correlation linking the proportion of tumor-reactive CD8+ and CD4+ TILs in each sample." (PMID 33198174, 2020). "Taking all three experiments together, there was a significant correlation after oHSV treatment or vehicle treatment between lower tumor volume and increased numbers in GP33+ CD8+ T cells (p < 0.001), gB498+ CD8+ T cells (p = 0.001) pan-CD4+ T cells (p = 0.019), but not pan-CD8+ T cells (p = 0.891)." (PMID 32198420, 2020). "However, combined ablation of both CD4+ and CD8+ cells led to faster tumor growth than in mice ablated of just CD8+ T cells, suggesting a non-redundant contribution of CD4+ T cells." (PMID 33220234, 2020). "Beside the already described down-regulation of MHC-I expression in tumor cells in vivo hampering CD8+ CTL recognition, it is now well established that insufficient response was due to the lack of efficient help provided to CTL by CD4+ Th cells." (PMID 33138029, 2020). "In the present study, one patient who received PF-04136309 had an increase in programmed cell death protein 1 (PD-1) + CD4+ and PD-1 + CD8+ cells in the tumor biopsy sample (data not shown), suggesting PF-04136309 also modulated PD-1 immune checkpoint in mPDAC." (PMID 31297636, 2020). "However, the role of CD4+T cells (MHC class II) in the TME is always been neglected and the immune response of single CD8+T cells is not enough to eliminate tumor cells In actual immunotherapy." (PMID 33169786, 2020). "A fraction of CD8+ TILs can be bystanders and recognize non-tumor related viral antigens, whereas CD4+ TILs can be both bystander and/or forkhead Box P3 (FOXP3)+ tumor-specific T cells, which may be endowed with regulatory T cell functions." (PMID 33198174, 2020). "Treatment with free DXR tended to decrease the number of both tumor infiltrating CD8+ and CD4+ T cells (non-significant, n.s.), which might be due to non-specific toxicity." (PMID 33086690, 2020).